IL1B (interleukin 1 beta)
Diseases named in the same sentence as IL1B in open-access papers (continued):
Sharing a sentence is not in itself a finding about the gene and the disease.
colitis (continued). "Recently, piperine has been shown to inhibit the levels of colonic NF-κB protein and the mRNA expression of pro-inflammatory mediators (TNF-α, IL-1β, IL-6, iNOS, and COX-2) in rats of TNBS-induced colitis." (PMID 35807865, 2022). "Our results of ELISA demonstrated that the serum levels of TNF-α, IL-1β and IFN-γ were increased in mice with DSS-induced colitis, but down-regulated after treatment with recombinant IGFBP5." (PMID 36389828, 2022). "Mice treated with MCC950, a specific NLRP3 inhibitor, experienced resolution of acute or chronic colitis by inhibiting ASC oligomerization, caspase-1 dependent activation of IL-1β and IL-18, and reducing pro-inflammatory cytokines." (PMID 36199683, 2022). "Comprehensive bioinformatics analysis using RRA, WGCNA, and Cytoscape, as well as in vivo validation using a classic mouse model of colitis revealed CXCL1, IL1B, MMP1, and MMP10 as signature genes of active UC." (PMID 35392084, 2022). "Also, the alteration of gut microbiota from P. tenera extract effectively alleviated colitis symptoms such as body weight loss, colon length loss, and diarrhea, and also attenuated the mRNA expression of pro-inflammatory cytokines (TNF-α, IL-6, IL-1β, and COX-2)." (PMID 35877732, 2022). "Its impact on colitis was evidenced by improving the biochemical markers TAC and GSH and the decrease in IL-1β, TNF-α, MDA, and MPO compared to the colitis control group." (PMID 35428860, 2022). "It was also found that mice genetically deficient in miR-223 display markedly exacerbated experimental colitis, as indicated by increased immune infiltration (neutrophils and monocytes), hyperactivated NLRP3, and IL-1β release." (PMID 36389791, 2022). "As expected, colitis mice treated with Bp7 and Bp8 exhibited lower concentrations of TNF-α and IL-1β (p < 0.05) and higher concentrations of IL-10 and IL-22 relative to the DSS group (p < 0.05)." (PMID 35681301, 2022). "Overactivity of pro-inflammatory factors such as IL-1β, IL-6, and TNF-α play important roles in inducing and maintaining colitis intestinal inflammation." (PMID 35645824, 2022). "Mechanistically, overexpression of PFKFB3 induced phospho-p65 and promoted the expression of IL-1β and tumor necrosis factor alpha (TNF-α) in the development of colitis and CAC." (PMID 36016583, 2022). "ADP, a danger signal released during colonic injury from IECs, activates NLRP3 inflammasomes via P2Y1 receptors and promotes phosphorylation of NLRP3 inflammasomes component ASC to increase IL-1β production, thereby worsening DSS-induced colitis in mice." (PMID 36590401, 2022). "In a dextran sulfate sodium-induced murine colitis model, acupuncture relieved colitis symptoms by suppressing pro-inflammatory NLRP3/IL-1β, and promoting both the antioxidant Nrf2/HO-1 and the M1 to M2 transition." (PMID 36712435, 2022). "The deficiency of CXCL13 resulted in significantly decreased expression of inflammatory cytokines IL-21, IL-1β, IL-1α, IL-17, IL-6 and TNF-α in colon sites of mice with colitis." (PMID 36172372, 2022). "Increased LGALS9 expression in humans is positively correlated with augmentation of T-cell markers and proinflammatory cytokines such as IL1B and IL6 in the affected intestines, which also has positive correlation to the severity of colitis." (PMID 35794311, 2022). "In a chemical-induced mouse model of colitis, L. fermentum CQPC04 reduced TNF-α, IFN-γ, IL-1β, IL-6, and IL-12, and increased IL-10 release in serum; it also downregulated NF-kB and up-regulated IL-10 expression in colon tissue." (PMID 35408849, 2022). "The mass accumulation of IL-6, IL-1β and TNF-α is one of the features of DSS-induced colitis, which amplifies the inflammatory cascades and accelerates the disease progression." (PMID 35211182, 2022).
colitis (continued). "Specifically, neutrophils, not monocytes, represent the predominant leukocyte recruited to the brain during acute colitis, and the resulting adhesive interactions with the cerebral endothelium drives an increased expression of CCL2 and IL-1β in the brain." (PMID 35379260, 2022). "Fermented soy gram, consisting of isoflavones, down-regulated IL-1β and up-regulated IL-10; hence, the permeability of intestinal cells decreased in TNBS-induced colitis." (PMID 35566252, 2022). "We used qRT-PCR to examine the mRNA expression levels of pro-inflammatory cytokines, including TNF-α, IL-6, and IL-1β, in colon tissue because higher protein and mRNA levels of these cytokines were observed in the DSS-induced colitis animal model." (PMID 36080669, 2022). "Overproduction of pro-inflammatory cytokines, such as TNF-α, IL-1β, and IL-6, is the typical feature of the DSS-induced colitis mouse model." (PMID 36033869, 2022). "Transcript levels of IL-6, IL-1β, and TNF-α were considerably higher in both colitis groups in this investigation." (PMID 35054518, 2022). "In animals with colitis, time‐related changes in the expression of colonic proinflammatory cytokines, IFN‐γ and IL‐1β, with an up‐regulation by experimental Day 21 (IL‐1β: p < 0.05 vs. control) and a normalization in the expression by Day 35 were observed." (PMID 36239298, 2022). "HHT alleviated DSS-induced colitis with downregulated TNF-α, IL-1β, IL-6, and CCL2 expression; reduced activation of nuclear factor-kappa B (NF-κB) signaling; and diminished proportion of recruited macrophages in colon tissues." (PMID 36211988, 2022). "In the DSS-colitis mice, supplementation of CPn or citrus residues (from juice extraction) decreased the expression of pro-inflammatory genes (TNF-α, IL-1β/-16, iNOS, ICAM-1) and colon weight/length ratio." (PMID 35399093, 2022). "D-limonene demonstrated anti-inflammatory effects in colitis by decreasing cytokines (NF-κB, TNF-α, IL-1β, and IL-6) when administered orally in rats." (PMID 36432834, 2022). "The DSS-induced colitis mouse model is primarily a macrophage/Th1/Th17 driven inflammatory model with increased levels of pro-inflammatory cytokines such as TNF-α, IL-1β and IL-6." (PMID 36365201, 2022). "In some studies involving the use of experimental colitis animal models, peripheral inflammation elevated the levels of proinflammatory cytokines such as TNF-α, IL-1β, and IL-6 in the hippocampus, cerebral cortex, and hypothalamus." (PMID 36275694, 2022). "Based on the results, the gene expression of inflammatory mediators counting TNF-α, IL-1β, and TLR4 noticeably amplified in the colitis group in comparison to the control group (P < 0.05)." (PMID 35432569, 2022). "TCA treatment during TNBS colitis also resulted in decreased colonic MPO, TNF-α, IL-1β, and INF-gamma levels." (PMID 36569849, 2022). "Kaempferol inhibits the NF-κB pathway to reduce IL-6, IL-1β, COX2, NOS, TNF-α, and reduces DSS-induced colitis." (PMID 35566252, 2022). "Corylin significantly reduced Ifnγ, Tnf-α, Il-6, Il-1β, Nlrp3, Asc, Pannexin, and Pro-caspase 1 mRNA expression and protein levels in DSS-induced colitis mice." (PMID 35269806, 2022). "Other studies demonstrated that colitis can increase the amounts of bacteria-derived toxic byproducts (LPS), pro-inflammatory cytokines (including TNF-α, IL-1β and IL-6), and gut leak." (PMID 36275694, 2022). "Through multiplex analysis, we found that DSS induces the release of pro-inflammatory cytokines, IL-1β and TNF-α, which facilitates the inflammation in the DSS-induced colitis mouse model." (PMID 35933374, 2022). "Network of cytokines including IL-1β, TNF-α, IL-6, IL-10, IFN-γ, and IL-18, have been reported to regulate mucosal inflammation in colitis, and IL-6, TNF-α are viewed as therapeutic targets in IBD." (PMID 35330829, 2022).
colitis (continued). "We then evaluated the effect of WT161 on IL-1β and IL-6 in the supernatant culture of colonic explants isolated from DSS-induced colitis mice and activated peritoneal macrophages induced by LPS + DSS." (PMID 35330829, 2022). "We also discovered that DSS activated the signaling pathway NF-κB and increased IL-1β, IL-6, and TNF-α in DSS-induced colitis mice." (PMID 36033869, 2022). "In this study, we found that the HDAC6 inhibitor WT161 exerts a protective effect in a DSS-induced colitis murine model and blocks NLRP3 inflammasome activation, as IL-1β release and ASC oligomerization were inhibited in the WT161-treated group." (PMID 35330829, 2022). "EVs from mouse BMSCs primed with a cocktail of cytokines (IL-1β, IL-6 and TNF-α) had higher efficacy in reducing the necrotic mucosal surface and collagen deposition in a dextran sulfate sodium-induced colitis model." (PMID 36341339, 2022). "SIRT6 transgenic mice showed lower levels of pro-inflammatory cytokines like TNF-a, IL-1β, and IL-6 in the dextran sulfate sodium salt (DSS)-induced colitis model than normal mice." (PMID 35517808, 2022). "Baicalein can alleviate colitis severity induced by TNBS by inhibiting the activation of NLRP3 inflammasome and production of IL-1β in the colon." (PMID 36090968, 2022). "Meanwhile, the levels of inflammatory factors TNF-α, IL-1β, and IL-6 were upregulated in DSS-induced colitis mice." (PMID 35630568, 2022). "Results showed that Shikonin dose-dependently alleviated mice colitis, down-regulated expression of F4/80, iNOS and CD86, decreased IFN-γ, IL-1β, IL-6 and TNF-α, while increased IL-10 in mice colon." (PMID 36059938, 2022). "The pro-inflammatory cytokines TNF-α, IL-1β, IL-6, IL-12, and IFN-γ levels in mice with DSS-induced colitis were apparently higher than those of mice in the normal group, but anti-inflammatory cytokine IL-10 was lower (P < 0.05)." (PMID 36171753, 2022). "Rutin was able to reduce cytokines such as IL-1β and reduce inflammation in the colon in trinitrobenzene sulfonic acid (TNBS) induced colitis." (PMID 35566252, 2022). "Colitis in the dual treated mice (i.e., LF82 + DSS) was accompanied by elevated proinflammatory cytokines in the colonic tissues including IL-17, IFNγ, IL-1β, and IL-6 compared to the mice treated with DSS only." (PMID 35381031, 2022). "ANP downregulated TNF-α, IL-1β, IL-6, IFN-α, and IFN-β mRNA levels in the colonic tissue in the mouse model of colitis (P < 0.05)." (PMID 35280696, 2022). "The increased IL-1b and TNF serum levels and enhanced HIF-1 and IL-10 expression in colitis mice were suppressed by CYN therapy, and the treatment facilitated IL-4, CCL2, and PPARγ expression." (PMID 36278202, 2022). "Our data suggest that pretreatment with Rg1 and ADSC + Rg1 markedly decreases the levels of TLR4 and MyD88, as well as the expression of TNF-α, IL-6, IL-1β, IFN-γ, and IL-17A in the DSS-induced mouse model of colitis." (PMID 35729638, 2022). "The mRNA and protein levels of IL-1β, TNF-α, and NF-κB/p65 in colonic tissue from the colitis mice were decreased after the STV-Na treatment." (PMID 35126813, 2022). "Conversely, overexpression of HIF-2α in intestinal epithelial cells lead to spontaneous DSS colitis in mice coinciding with an increased expression of TNF, IL-1β and IL-6, whilst deletion of HIF-2α in mice with DSS-induced colitis has a protective effect." (PMID 35769556, 2022). "Another important pro-inflammatory cytokine is IL-1β, which has been found to exacerbate IBD in both experimental colitis and colitis in humans when its secretion is increased." (PMID 35327370, 2022). "To further estimate the influence of MOP upon inflammation in colitis, we detected the levels of TNF-α, IL-1β, IL-6, and IL-10 in the serum from the control, DSS, and DSS + H MOP groups." (PMID 35911761, 2022).
colitis (continued). "Our current results indicated that rCsCP or CsCA might down-regulate the inflammatory responses of colitis mice via elevating Treg cells in both the spleens and MLNs, inducing the release of Th2 cytokines (IL-10, IL-4 and IL-13), and restraining the production of IL-1β and IL-2 cytokines in serum." (PMID 36084127, 2022). "The study indicated that, a large number of proinflammatory factors (IFN-γ, IL-1β, IL-6, and TNF-α) were produced in the serum and colonic tissues after colitis was induced by DSS in mice, while the anti-inflammatory factors (IL-10 and IL-4) decreased." (PMID 36159803, 2022). "In this study, the IL-1β and TNF-α levels were much higher in the DSS-induced colitis mice in contrast to control mice." (PMID 35126813, 2022). "In the present study, the levels of IL-6, IL-17A, IL-1β, and TNF-α were increased, accompanied by increased expression of TLR5/MyD88/NF-κB pathway in TNBS induced colitis rats." (PMID 35571126, 2022). "Staphylococcus aureus has been shown to suppress colitis and related CRC by activating Nlrp3, and Bacillus fragilis inhibits the secretion of IL-1β and IL-18 regulated by Nlrp3." (PMID 35954484, 2022). "In addition, plasma IL-1β levels were also significantly increased in IEC AMPK KO mice, indicating that loss of IEC AMPK activity might contribute to the development of a low grade basal chronic inflammation during DSS-induced colitis." (PMID 35203241, 2022). "In vivo murine studies revealed that KJK exposure increases the body weight and colon length, while reducing colonic epithelial injury, and the expression of inflammatory factors in colitis tissues such as TNF-α, IL-6, and IL-1β." (PMID 35774753, 2022). "In accordance with our study, Th1-derived TNF-α, Th17-derived IL-1β, and IL-6 were significantly increased in DSS-induced colitis mice compared to the control." (PMID 36176442, 2022). "In a DSS-induced colitis model, NLRP3 (−/−) mice were shown to release less IL-1β, a central factor in the pathogenesis of IBD, and NLRP3 (−/−) mice were less likely to exhibit colitis than wild-type controls." (PMID 35677444, 2022). "The effects of AOS on proinflammatory cytokines were further investigated by ELISA analysis of IL-1β, IL-6, TNF-α, IFN-γ, and IL-10 levels in the serum of DSS-induced colitis mice." (PMID 35889822, 2022). "Macrophages in the colon will trigger and exacerbate DSS-induced colitis by releasing cytokines, such as IL-6, TNF-α, and IL-1β." (PMID 36189321, 2022). "Consistent with previous studies, our results indicated that GTP inhibited the activity of NF-κB and MPO, the expression of TNF-α, IL-1β, IL-6, iNOS, and COX-2, and the production of NO and PGE2 in colon tissues of mice with DSS-induced colitis." (PMID 35807865, 2022). "It suppressed the inflammatory response via the attenuation of TNF-α, IL-1β, IL-6, and MPO activity in colitis rats in TNBS-induced colitis." (PMID 36235004, 2022). "Colitis is characterized by abnormal levels of inflammatory cytokines, especially TNF-α, IL-6, and IL-1β." (PMID 35681301, 2022). "M2 macrophage-derived exosomes upregulated Treg cells and IL-4, reduced the production of the proinflammatory cytokines IL-1β, IL-6 and IL-17A, reduced the severity of DSS-induced colitis in mice, and played a protective role in colitis." (PMID 36045437, 2022). "In conclusion, this is the first report showing that MNS reduced intestinal tissue damage, attenuated macrophage infiltration, and regulated IL-1β and IL-12 pro-inflammatory cytokine secretion in the mouse colon with DSS-induced colitis." (PMID 35784693, 2022). "Limited studies in models of chemically-induced colitis provide evidence that BDNF expression is reduced in the hippocampus (DNBS) and forebrain (DSS) with IL-1β expression elevated in DSS models." (PMID 34983592, 2022).
colitis (continued). "Isolated from egg white proteins, MLGATSL, DEDTQAMPFR, DEDTQAMPF, and MSYSAGF significantly inhibited the IL-8 and TNF-α secretion and also down-regulated the mRNA expression of TNF-α, IL-17, IL-6, MCP-1, IL-1β, and IFN-γ in colitis mice." (PMID 35406093, 2022). "Our study showed that blockage of BAFF activity effectively inhibited IL-1β, TNF-α, and IL-6 gene expression in colonic tissues from DSS-induced colitis mice." (PMID 35320937, 2022). "The authors also demonstrated the release of cytokines (e.g., IL-1β, IFN-γ, and TNF-α) from cytotoxic T cells (CTLs) and the high expression of chemokine receptor genes on colitis-associated T cells in patients with irAE colitis, which may be involved in the development of irAE colitis." (PMID 35740355, 2022). "Blocking α2-adrenergic receptors down-regulate TNF and IL-1β and improve 2,4,6-trinitrobenzenesulfonic acid (TNB)-induced colitis." (PMID 35646918, 2022). "Mechanistically, overexpression of PFKFB3 induced phospho-p65 and promoted the expression of IL-1β and TNF-α in the development of colitis and CAC." (PMID 36016583, 2022). "The production of proinflammatory mediators, including IL-1β, IL-6, TNF-α, IL-2, IL-17, and IFN-γ, plays a critical role in DSS-induced colitis in mice." (PMID 34804049, 2021). "For example, in DSS-induced colitis, TpH1−/− mice produce lower levels of the pro-inflammatory cytokines TNF-α, IL-1β, and IL-6 and have reduced macrophage infiltration when compared to TpH1+/+ mice." (PMID 34502396, 2021). "The mRNA expression of IL-1β, IL-18, IL-6, TNF-α, IFN-γ, ICAM-1, and VCAM-1 was markedly (all p < 0.01) up-regulated in DSS-induced colitis group, while the IL-10 expression was significantly (p < 0.01) down-regulated." (PMID 33859564, 2021). "The results showed that ARS treatment notably downregulated the mRNA and protein expression of IL-1β, IL-6, TNF-α, and the protein ratio of p-p65/p65 and p-IκBα/IκBα in colon tissues in colitis mice (p < 0.01)." (PMID 33767628, 2021). "The colitis-characterized pro-inflammatory cytokines such as TNF-α secreted by epithelial layer cells and IL-1β of colon homogenate were significantly decreased in rTsPmy-treated mice in comparison to PBS-treated mice." (PMID 34336843, 2021). "In intrarectal administration of TNBS-induced colonic inflammation model, EA at ST36 decreased TNF-α, IL-6, and IL-1β levels in plasma and MPO activities in colonic tissues." (PMID 35095910, 2021). "The level of IL-1β, IL-6, and TNF-α in the colon samples were found to be increased in response to the induction of colitis in mice, whereas, significantly reduced (p < .01) after CD–Cur–CANPs treatment." (PMID 34121560, 2021). "After mice with TNBS-induced colitis were treated by intragastric administration of ginsenoside Rb1, the levels of pro-inflammatory cytokines (TNF-α, IL-1β, and IL-6) declined, while the levels of anti-inflammatory cytokines (IL-10) increased." (PMID 33462754, 2021). "It was recently established that loganin at the doses of 80 and 160 mg/kg and morroniside at the doses of 90 and 180 mg/kg significantly decreased the expression of IL-1β and TNF-α in colon tissues of mice with dextran sodium sulfate-induced colitis." (PMID 34834710, 2021). "After MSC-Exo treatment, the colon length in colitis mice increased; colon inflammatory injury decreased; TNF-α, IL-6, IL-1β, IL-17, and IL-18 levels decreased; and Claudin-1, ZO-1, and IκB levels increased." (PMID 34249964, 2021). "In the sedentary colitis mice fed either SD or HFD, the mRNA expression of TNF-α, IL-1β and IL-6 was significantly increased compared with the respective values obtained in the group of non-exercising (sedentary) animals fed an SD (p < 0.05)." (PMID 33557311, 2021). "The colitis model group expressed significantly higher levels of colonic TNF-α, IL-1β, and IL-6, and lower levels of IL-10 compared with the control group." (PMID 35071260, 2021).